ENSG00000302642 (novel transcript)
Gene: Long non-coding RNA gene on chromosome 10 (22,225,568 to 22,245,593, reverse strand). Ensembl gene ENSG00000302642.
Gene Ontology:
Molecular function: triplet codon-amino acid adaptor activity
Biological process: translation